HDAC6 (histone deacetylase 6)
Diseases named in the same sentence as HDAC6 in open-access papers (continued):
Sharing a sentence is not in itself a finding about the gene and the disease.
tauopathy (continued). "Overall, our data warrant a careful evaluation of whether targeting, depleting, or inactivating HDAC6 will provide therapeutic utility in either AD or other tauopathy patients." (PMID 33139698, 2020). "Furthermore, the tau hyperphosphorylation phenotype observed in mice with tauopathy can be reversed by HDAC6 inhibition-mediated tau acetylation." (PMID 30270813, 2018). "Given that HDAC6 inhibition similarly augments axonal transport through enhanced tubulin acetylation, these findings suggest that reduced HDAC6 activity would also decrease tau burden and cognitive deficits in tauopathy." (PMID 25031639, 2014). "After we initiated these studies, a second mechanism by which HDAC6 inhibition might affect tauopathy was described." (PMID 24576665, 2014). "The decrease in tubulin acetylation and increased HDAC6 observed in patients with AD and other tauopathies is indicative of a disrupted microtubular network, which would be expected to contribute to the pathophysiological changes associated with disease progression." (PMID 25031639, 2014). "The ability to reduce both tau and αSyn pathologies with a single small molecule HDAC6 inhibitor has therapeutic appeal, not only because such a molecule might be used to treat both tauopathies and α-synucleinopathies, but also because these pathologies often coexist in patients." (PMID 41330635, 2026). "Additionally, HDAC6-regulated acetylation sites have been described as disease-specific markers for 3R/4R tauopathies and 3R tauopathies, which may indicate some differences in PTMs and even aggregation propensity of tau among different tauopathies." (PMID 37832941, 2024). "HDAC6 reversibly regulates tau acetylation, but its role in tauopathy progression remains unclear." (PMID 33139698, 2020). "Notably, these data provide multiple, related mechanisms by which HDAC6 inhibition might have benefits in tauopathies." (PMID 24576665, 2014). "Therefore, HDAC6 inhibitor could prevent axonal dysfunction, thereby slowing tauopathy progression." (PMID 34326423, 2021). "Here, we evaluate and compare the distribution of HDAC6 and its phosphorylated form in human brains obtained from patients affected by three forms of parkinsonism: two synucleinopathies (PD and MSA) and a tauopathy (progressive supranuclear palsy, PSP)." (PMID 32655357, 2020). "In addition, loss of HDAC6 restored cognitive function without impacting Aβ plaque burden in a transgenic mouse model of AD, and also rescued the abnormal behavioral phenotype in a Drosophila model of tauopathy." (PMID 23962722, 2014). "We now demonstrate significantly increased acetylated tau in tauopathy mice lacking HDAC6, further validating HDAC6 as a bona fide tau deacetylase in vivo." (PMID 33139698, 2020). "We compared the expression of phospho-HDAC6 in PD, the synucleinopathy MSA, and the tauopathy PSP." (PMID 32655357, 2020). "However, HDAC6 KD in tauopathy mice did not lower tau pathology, and HDAC6 knock-out resulted in increased tau pathology and shortened lifespan in tau transgenic mice." (PMID 41330635, 2026). "The acetylation state of MTs contributes to stability and histone deacetylase 6 (HDAC6) is a major regulator of MT acetylation status, suggesting that pharmacological HDAC6 inhibition could improve axonal function and may slow the progression of tauopathy." (PMID 34326423, 2021). "As such, the use of HDAC6 inhibitors to alleviate tau burden through the enhanced acetylation on KXGS motifs represents a very promising therapeutic strategy that should be investigated as a potential treatment for AD, as well as other tauopathies, including chronic traumatic encephalopathy." (PMID 23962722, 2014).
Anxiety (12 papers, 2012 to 2026). Intense feelings of nervousness, tension, or panic often arise in response to interpersonal stresses. "HDAC6 gene-deficient mice show less anxiety, more hyperactivity, and less depression, and HDAC6 specific inhibitors have antidepressant-like effects in mice." (PMID 35449808, 2022). "In this study, we found that Hdac6 is highly expressed in serotonergic neuron, and that loss of Hdac6 deacetylase activity leads to hyperactivity, less-anxiety and antidepressant-like behavior in mice." (PMID 22328923, 2012). "We found that Hdac6-deficient mice exhibit hyperactivity, less anxiety, and antidepressant-like behavior in behavioral tests." (PMID 22328923, 2012). "It has been observed that HDAC6 deficiency may cause anxiety-like behavior in males and a slight anti-depressive effect in females." (PMID 37373121, 2023). "Furthermore, HDAC6 activity has been associated with emotional behavior like activity, anxiety, and depression." (PMID 36129937, 2022). "Furthermore, HDAC6 affects the emotional behaviour of experimental animals since Hdac6-deficient mice exhibit hyperactivity, less anxiety, and anti-depressant-like behaviour." (PMID 36129937, 2022). "Interestingly, HDAC6 deficiency in mice resulted in hyperactivity and reduced anxiety, and depression-like behavior." (PMID 27216537, 2016). "The potential benefits of a therapeutic approach must be considered in the context of patient safety, and in this regard HDAC6 knock-out mice develop normally, with minor effects on bone density and reported reductions in anxiety and depressive behavior." (PMID 41330635, 2026). "Depletion of Hdac6 expression in 8-week old mice resulted in decreased open area traveling time suggesting a potential increase in anxiety-like behavior (WT: 33.9 ± 6.4 s; CF: 41.1 ± 6.4 s; HDA: 11.0 ± 1.6 s: DKO: 20.6 + 5.0 s)." (PMID 33004910, 2020). "Although Hdac6 KO mice exhibited less anxiety and antidepressant-like activity in these tests, we should point out the possibility that such behavior is, in part, responsible for increased locomotor activity under a novel environment." (PMID 22328923, 2012). "Although, at present, the molecular mechanism of how inhibition of Hdac6-mediated protein deacetylation leads to hyperactivity, less-anxiety, and antidepressant-like activity still remains elusive, we have obtained some insight into this issue." (PMID 22328923, 2012). "We found that male Hdac6−/− mice exhibit hyperactivity and certain anxiety." (PMID 37373121, 2023). "However, the phenomenon of anxiety is inconsistent; some reports demonstrate that knockout of Hdac6 might have an anxiolytic-like effect on mice, while another supports our results, in which an increase in anxiety-like behavior is reported for grouped male and female Hdac6 null mice." (PMID 37373121, 2023). "Similar to the experiments performed with TubA, mice with an absence of HDAC6 protein present normal anxiety, motor function, motor activity, and habituation." (PMID 32697819, 2020). "HDAC6−/− mice spent slightly less time in corners (time spent in zone), indicating no major difference in anxiety." (PMID 32697819, 2020).
atherosclerosis (12 papers, 2011 to 2025). A disease characterized by the build-up of fatty material and calcium deposition in the arterial wall resulting in partial or complete occlusion of the arterial lumen. "Further, elevated HDAC6 activity has been implicated in the development of atherosclerosis, and tubacin enhances the atheroprotective effects of eNOS." (PMID 34220539, 2021). "Although HDAC7 mice are embryonic lethal, HADC6 deficient mice are viable and fertile, and it will be interesting to see in future studies if regression of atherosclerosis is impaired in HDAC6 deficient mice upon statin treatment." (PMID 22163030, 2011). "Collectively, this study establishes HDAC6 as a potential therapeutic target for atherosclerosis intervention." (PMID 41444216, 2025). "Our findings establish HDAC6 as a protective regulator in atherosclerosis, which maintains lipid metabolic homeostasis by modulating the STAT3-CD36/SR-A axis." (PMID 41444216, 2025). "In a murine macrophage model of atherosclerosis, another histone deacetylase, HDAC6, was shown to promote nicotine-mediated inflammation and pyroptosis via deacetylation of p65, and activation of NF-kB and NLRP3 transcription." (PMID 39529883, 2024). "Nicotine promotes atherosclerosis through the induction of NLRP3-dependent macrophage pyroptosis; HDAC6 depletion abolishes nicotine-caused pyroptosis by inhibiting NLRP3 transcription." (PMID 35565726, 2022). "Targeting HDAC6 attenuates nicotine-induced macrophage pyroptosis via the NF-kappaB/NLRP3 pathway in atherosclerosis." (PMID 35910382, 2022). "In summary, lncRNA NORAD enhanced vascular endothelial cell injury and atherosclerosis through suppressing VEGF gene transcription via enhancing H3K9 deacetylation by recruiting HDAC6." (PMID 34307380, 2021). "Endothelial barrier integrity is compromised in the process of atherosclerosis, and selective inhibition of HDAC6 in human pulmonary artery ECs has been shown to prevent TNF-α–induced EC barrier dysfunction and endotoxin-induced pulmonary edema." (PMID 34220539, 2021). "Given that macrophages are important players in many inflammatory diseases, such as atherosclerosis and chronic inflammation, our findings provide a basis for targeting HDAC6 in the management of inflammatory disorders." (PMID 25330030, 2014). "The HDAC6 NEDDylation molecular pathway might regulate genes related to endothelial control of vasomotor tone, reactivity, and atherosclerosis." (PMID 34220539, 2021). "Though we have some understanding of how augmented HDAC6 activity is deleterious to cultured ECs, the role of HDAC6 in atherosclerosis in vivo is still unknown." (PMID 34220539, 2021). "Notably, we investigated the use of tubacin, a small molecule inhibitor of HDAC6, in a mouse model of atherosclerosis." (PMID 34220539, 2021). "In this study we found that pharmacologic inhibition of HDAC6 with tubacin restores endothelial-dependent relaxation, prevents the development of vascular stiffness—one of the integrated measures of vascular health in vivo—and significantly reduces plaque burden in a mouse model of atherosclerosis." (PMID 34220539, 2021). "Except for nucleus lncRNA NORAD and HDAC6, cytoplasmic lncRNA NORAD and HDAC6 may also play a suppressive role in VEGF expression through associating with VEGF protein and subsequently enhancing the deacetylation of VEGF protein in vascular endothelial cell injury, atherosclerosis, and CAD." (PMID 34307380, 2021). "Studies are warranted to determine the specific effects of HDAC6 inhibition by MLN4924 on endothelial function and atherosclerosis." (PMID 34220539, 2021). "In this study, the authors demonstrated that increased histone deacetylase 6 (HDAC6) downregulated CSE and H2S production via posttranslational modifications, thus leading to endothelial cell dysfunction and the development of atherosclerosis." (PMID 32038245, 2019).
cognitive deficits (12 papers, 2013 to 2025). "We show here for the first time that pharmacological inhibition of HDAC6 with the brain-penetrating inhibitor ACY-1083 reverses cisplatin-induced cognitive impairment as assessed in multiple behavioral tests." (PMID 30270813, 2018). "We investigated the effects of the brain-penetrating HDAC6 inhibitor ACY-1083 on cisplatin-induced cognitive deficits and neuronal mitochondrial damage." (PMID 30270813, 2018). "Given the positive correlation of tau pathology with cognitive impairment in AD patients, we examined how HDAC6 inhibition in vivo correlates with behavior and pathophysiological changes measured in treated rTg4510 mice." (PMID 24576665, 2014). "Thus, HDAC6 inhibition improves cisplatin-induced cognitive deficits by reversing mitochondrial and synaptic functional impairments." (PMID 33374719, 2020). "Indeed, we showed recently that cell therapy with mesenchymal stem cells or a pharmacolgocial intervention with PFT-μ and HDAC6 inhibitor both reverse cisplatin-induced neuronal mitochondrial abnomarlities as well as cognitive impairment in mice." (PMID 32197663, 2020). "Reducing HDAC6 activity has been reported to ameliorate cognitive deficits in an AD mouse model." (PMID 29844403, 2018). "Furthermore, we demonstrate that deacetylation of α-tubulin and hyperphosphorylation of tau were part of the mechanism contributing to cisplatin-induced cognitive impairment, and that HDAC6 inhibition reversed these pathological changes as well." (PMID 30270813, 2018). "Especially, the fact that complete loss of Hdac6 did not cause any overt phenotype but improved cognitive function in a disease model strongly suggests that targeting HDAC6 could be a promising strategy to treat cognitive impairment in neurodegenerative diseases such as AD." (PMID 23184605, 2013). "A study in mice found that the histone deacetylase 6 inhibitor, ACY-1215, improved established cisplatin-induced cognitive impairment by restoring mitochondrial and synaptic damage." (PMID 32684930, 2020). "CM-695 is a potent HDAC6 and PDE9 inhibitor that, after chronic administration, ameliorates the cognitive impairment and amyloid pathology evident in aged-Tg2576 mice." (PMID 31281249, 2019). "Treatment with 14 doses of the HDAC6 inhibitor ACY-1083 starting 3 days after completion of cisplatin treatment, completely reversed this cognitive deficit (post-hoc test, p = 0.0074)." (PMID 30270813, 2018). "Interestingly, APPPS1-21 mice crossed with HDAC6−/− mice improved their cognitive deficits without changing the amyloid-beta plaque load." (PMID 24576665, 2014). "For instance, in a mouse model of AD, genetic ablation of HDAC6 alleviated cognitive impairment without impacting plaque burden, which may suggest that beneficial consequences of loss of HDAC6 expression are due to effects on endogenous tau, though this has not yet been assessed in this model." (PMID 25031639, 2014). "However, the therapeutic effect of targeting HDAC6 may not readily translate to all conditions of cognitive impairment and other neurodegenerative diseases." (PMID 23184605, 2013).
lung adenocarcinoma (12 papers, 2016 to 2026). A carcinoma that arises from the lung and is characterized by the presence of malignant glandular epithelial cells. "To determine the HDAC6 expression level in lung adenocarcinoma, we queried the TCGA lung adenocarcinoma database for the variant expression of HDAC6 between tumor and normal lung adjacent tissues." (PMID 36639650, 2023). "Smad3 interacts and cooperates with HDAC6 during EMT in A549 lung adenocarcinoma cells; HDAC6 is well known as a regulator of tubulin acetylation causing microtubule instability and blocking cell migration." (PMID 27367735, 2016). "High expression of HDAC6 associated with poor outcome in lung adenocarcinoma." (PMID 33162791, 2020). "Moreover, transforming growth factor-β (TGF-β)-induced EMT is associated with HDAC6-dependent deacetylation of α-tubulin in A549 lung adenocarcinoma cells, and acetylated α-tubulin serves as a novel regulator and marker of EMT1,23." (PMID 30504808, 2018). "The data revealed that the mRNA levels of HDAC6 were substantially increased in lung adenocarcinoma tissues (n = 509) compared with normal lung tissues (n = 56)." (PMID 36639650, 2023). "Our study provides an intriguing mechanism of HDAC6 inhibition, suggesting that HDAC6 is an attractive therapeutic target for lung adenocarcinoma." (PMID 36639650, 2023). "In the present study, we, therefore, investigated HDAC6 expression in human lung adenocarcinoma tissues and the underlying mechanism of ERK phosphorylation using the HDAC6 inhibitor trichostatin A (TSA) and small interference to HDAC6 (siHDAC6)." (PMID 36639650, 2023). "The HDAC6 is abundant in A549 and H1355 cells in lung adenocarcinoma, but its expression levels are relatively lower in normal lung epithelial NL20 cells." (PMID 33162791, 2020). "Overexpression of HDAC6 is a common feature in lung adenocarcinoma cell lines and negatively correlates with prognosis of lung adenocarcinoma patients." (PMID 27499032, 2016). "The current study demonstrates HDAC6 is required for activation of Notch-1 signaling in response to TGF-β1 in human lung adenocarcinoma cells." (PMID 27499032, 2016). "Our study suggests an HDAC6–dependent deacetylation mechanism of HSP90 in human lung adenocarcinoma cell line A549 as a feature of TGF-β1 stimulation." (PMID 27499032, 2016). "For example, both the bromodomain inhibitor JQ1, and the HDAC6 inhibitor ricolinostat were found to attenuate Treg cell suppressive function, facilitate immune-mediated tumor growth arrest, and lead to prolonged survival of mice with lung adenocarcinomas." (PMID 35874729, 2022). "Given that overexpression of HDAC6 is common in lung adenocarcinoma cell lines and confers resistance to gefitinib, interplay amongst TGF-β, Notch signaling and HDAC6 may be implicated in EMT and resistance to EGFR-TKI." (PMID 31681582, 2019). "TGF-β was reported to induce EMT through HDAC6-dependent deacetylation of α-tubulin in lung adenocarcinoma A549 cells; thus, α-tubulin acetylation could serve as a marker for EMT1." (PMID 30504808, 2018). "Next, we investigated whether HDAC6 was related to prognosis in lung adenocarcinoma." (PMID 36639650, 2023). "H460 and A549 lung adenocarcinoma cells were treated with trichostatin A (TSA), an HDAC6 inhibitor, or transfected with siHDAC6." (PMID 36639650, 2023). "Additional competition assays performed in lung adenocarcinoma cell A549 lysate also identified HDAC1, HDAC2, and HDAC6 as targets." (PMID 37322067, 2023). "CAY10603, an inhibitor of HDAC6, acted synergistically with gefitinib to induce the apoptosis of lung adenocarcinoma cell lines by destabilizing EGFR, whereas sorafenib activated EGFR signaling by stabilizing HDAC6." (PMID 36076996, 2022).